TYMS (thymidylate synthetase)
Diseases named in the same sentence as TYMS in open-access papers (continued):
Sharing a sentence is not in itself a finding about the gene and the disease.
cancer (continued). "5-FU, an inhibitor of thymidylate synthetase, has been used to treat cancer for several decades; it causes side effects when administered systemically which include myelosuppression and stomatitis which develop serious complications." (PMID 22159640, 2012). "Additionally, TYMS has been previously associated with neuroendocrine differentiation in other types of cancer." (PMID 39518911, 2024). "Therefore, we preliminarily defined c4_SOD2 as suppressive cancer-associated pericytes (sup-CAPs) and c5_TYMS as promoted cancer-associated pericytes (pro-CAPs)." (PMID 39835116, 2024). "For example, TYMS, associated with folate-mediated one carbon metabolism and a target for some drugs such as Fluorouracil Injection (5-FU) and Capecitabine, was found to be upregulated in cancer stages with larger weights in stage III than in other stages." (PMID 35448980, 2022). "The aim of this study was to determine whether the five genetic polymorphisms within two genes (DPYD, TYMS) are associated with severe toxicity in patients with cancer receiving fluoropyrimidine-based chemotherapy." (PMID 32695278, 2020). "Furthermore, we highlight the association of the TYMS 3R/3R genotype with relapse-free cancer protection and the increased survival time of these patients in relation to those with the TYMS 2R allele." (PMID 33369477, 2020). "In fact, ectopic TYMS expression has been shown to promote cell proliferation in vitro, and the high expression of TYMS in tumor tissue is also associated with poor clinical outcome in some types of cancers." (PMID 25739012, 2015). "TYMS overexpression was associated with deletions at 5q21 (p < 0.0001), 6q15 (p < 0.0001) and 3p13 (p = 0.0083) and gradually increased with the total number of these deletions present in the respective cancer sample (p < 0.0001)." (PMID 25762627, 2015). "Therefore, the ability to efficiently lower TYMS catalytic activity using a continuous maintenance regimen without the risk of inducing reciprocal feedback mechanisms such as TYMS overexpression is a key strategy to improve outcomes for patients with difficult-to-treat cancers." (PMID 37097751, 2023). "Moreover, this last polymorphism protects TYMS-3R/3R genotype carriers against cancer recurrence." (PMID 33369477, 2020). "Although the promoter TSER polymorphism was identified in a cis-acting enhancer element of the TYMS gene and is thought to affect TYMS mRNA expression, several molecular epidemiological studies reported contrary results of the associations between this variant and cancer risk." (PMID 16723031, 2006). "Knockdown of TYMS has been shown to increase apoptosis in certain cancers and negatively affect the metastatic potential of advanced cancers, including HCC." (PMID 40075750, 2025). "Telomerase reverse transcriptase (TERT, −5.4 kcal mol−1) and thymidylate synthase (TYMS, −4.06 kcal mol−1) are both involved in sustaining the uncontrolled proliferation characteristic of cancer cells." (PMID 40733037, 2025). "In HCC tissues and cell lines, TYMS knockdown has demonstrated anti-proliferative effects and has been reported to reduce cancer aggressiveness via the TS/DYPD axis." (PMID 40075750, 2025). "While the relationship between TYMS and cancer has been extensively studied, its role in NAFLD, AF, or inflammation requires further exploration." (PMID 38549670, 2024). "Targeting RG4s to overcome resistance mechanisms has been demonstrated for the anti-cancer drug 5-fluorouracil (5-FU), an inhibitor of the thymidylate synthase (TYMS) enzyme involved in DNA synthesis." (PMID 38828391, 2024). "This process is also regulated via FOXM1 in the same way as other cancer-related genes, including TYMS, another major protagonist in our screen that was found to be vital to metastatic cells." (PMID 39518122, 2024). "Thymidylate synthase (TYMS), a key enzyme in the production of the pyrimidine dTMP, is transcriptionally elevated in many cancer types." (PMID 37949226, 2023).
cancer (continued). "For example, there are >900 publications in PubMed that link either anti-cancer drug resistance or worse clinical outcome in patients with tumors expressing elevated TYMS levels." (PMID 37106126, 2023). "TYMS overexpression is a general event in human carcinogenesis, and is closely related to cancer cell functions including proliferation, invasion, and cell division." (PMID 37682862, 2023). "For these reasons, TYMS has been a target of cancer intervention since the 1950s, and chemotherapy agents such as 5-fluorouracil (5-FU), methotrexate, and pemetrexed are still in use for patients with colon, pancreatic, and non–small cell lung cancer." (PMID 37097751, 2023). "In order to further explore the mechanism of TYMS playing a role in promoting cancer, transcriptomic sequencing was carried out, and differentially expressed genes related with antioxidant capacity such as Nrf2 were identify." (PMID 37682862, 2023). "TYMS upregulation correlates with the invasive phenotype of cancer cells, corresponding with the epithelial-to-mesenchymal transition (EMT) process that is manifested in metastasis." (PMID 37894370, 2023). "5-FU has been used for treating CRC cancer, but 5-FU drug resistance occurs, at least in part, due to upregulated TYMS, thereby leading to the prevalent unresponsiveness in patients." (PMID 36941257, 2023). "Comparison of TYMS expression across human cancer types from the TCGA dataset analyzed using the UALCAN portal revealed that TYMS is expressed at higher levels in all tumor types compared to normal tissues." (PMID 37106126, 2023). "Since there is a possible relationship between cancer metastasis and drug resistance, we explored the potential role of TYMS in invasiveness regulation in cancer cells." (PMID 35740289, 2022). "Our results identified many novel variants located in essential genes to cancer (DPYD, TYMS, MTHFT, and GSTT1), infectious diseases (IFNL4), and psychiatric treatments (CYP2D6)." (PMID 35743738, 2022). "Secondly, survival was predicted using 10 oncology panels (transcriptome, cancer progression and pathways, metabolic pathways, immuno-oncology, and host response), and TYMS was highlighted." (PMID 35052318, 2022). "We previously demonstrated the efficacy of the PPRH approach on the KRAS and TYMS genes, and the modulation of their expression resulted in a reduction in cancer cell viability." (PMID 36613820, 2022). "It has been reported that CD44, MKI67 and TYMS are overexpressed in many cancer types, including DTC, and regulate glucose metabolism by targeting different genes." (PMID 35528004, 2022). "We propose that MTHFD2 is crucial for sustaining the production of CH2-THF, generated as a substrate for TYMS in cancer cells." (PMID 35228749, 2022). "The high level of TYMS is conducive to the development of cancer, so it is considered to be an oncogene." (PMID 34858842, 2021). "The upregulation of a number of rate-limiting enzymes in pyrimidine biosynthesis such as deoxythymidylate kinase (DTYMK), thymidylate synthase (TYMS), and thymidine kinase 1 (TK1) in HCC is associated with cancer stemness and poor prognosis." (PMID 33747521, 2021). "Antifolates, such as PMX, primarily target TYMS and are still used as chemotherapeutic agents for many cancers." (PMID 34646134, 2021). "For example, 5-fluorouracil (5-FU), an uracil analog, is a commonly used clinical drug for cancer treatment, which targets thymidylate synthase (TYMS) to affect the de novo nucleotide synthesis pathway." (PMID 38650282, 2021). "In fact, in the clinical evidence, in the patients with metastatic or advanced CRC, lower TYMS expression level in cancer tissues is indeed a better outcome to 5-FU-included chemotherapy compared with the higher expression level." (PMID 34947902, 2021). "Due to its pivotal role in the de novo synthesis of pyrimidines, TYMS is an established drug target for cancer treatment." (PMID 34454516, 2021).
cancer (continued). "There are many studies in the literature demonstrating prognostic and predictive values of TYMS presence in cancer, however, its role as a marker of HCC metastasis is not known." (PMID 34858842, 2021). "Thymidylate synthase (TYMS) has been widely studied as an anti-cancer target due to its essential role in the de novo synthesis of 2’-deoxythymidine-5’-monophosphate (dTMP), a critical precursor for DNA biosynthesis." (PMID 32708710, 2020). "Overall, our study identified a tumor-promoting lincRNA — lincNMR — and unveils its mechanism along a YBX1–RRM2 / TK1 / TYMS axis in regulating nucleotide metabolism and governing the cancer cell fate between proliferation and senescence." (PMID 32587247, 2020). "According to TCGA database, TYMS expression was statistically higher in CRC tissues compared to adjacent tissues, indicating the positive effects of TYMS in cancer development." (PMID 33046972, 2020). "TYMS inhibition affects highly proliferative cells (e.g., cancer cells) and has been established as a classic chemotherapeutic treatment during the last few decades." (PMID 32708710, 2020). "Since its development in 1957, the nucleobase 5-fluorouracil (5-FU) has become one of the most widely used TYMS inhibitors for the treatment of different types of cancer, either as a single agent or in combination with other chemotherapeutics." (PMID 32708710, 2020). "In cancer cells, HpTYMG-G4-T decreased TYMS mRNA and protein levels, leading to cell death, and showed a synergic effect when combined with 5-fluorouracil." (PMID 32708710, 2020). "Since TYMS is involved in the de novo synthesis of dTTP, inhibition of TYMS expression using HpTYMS-G4-T was expected to reduce the viability of cancer cells and to produce a higher effect when the incubation was carried out in thymidine deficient medium." (PMID 32708710, 2020). "Reduced dTTP pools, evidenced by CDC8/DTYMK and CDC21/TYMS, can increase doxorubicin cytotoxicity in cancer cell lines." (PMID 31660150, 2019). "The overexpression of CDK1, TYMS, CDT1, and CCNA2 and the underexpression of PRKACB were associated with tumorigenesis, defective cell signaling, or aberrant metabolism in other cancers." (PMID 31205467, 2019). "Thymidylate synthase (TYMS) is an essential enzyme for the de novo synthesis of deoxythymidine monophosphate (dTMP) and has been a primary target for cancer chemotherapy." (PMID 29735940, 2018). "In the in-cell CETSA experiment with thymidine, two important drug targets for cancer therapy were directly revealed; TYMS targeted by e.g. fluorouracil and diverse antifolates, and RNR, targeted by e.g. clofarabine and gemcitabine." (PMID 30521565, 2018). "Another commonly used anti-cancer treatment, 5-fluorouracil (5-FU), is known to inhibit thymidylate synthase (TYMS), which catalyzes the transfer of a one-carbon unit from methylene-THF onto dUMP to make dTMP." (PMID 30159313, 2018). "TYMS, the action target of 5-FU, has been studied intensively for the past decade because of its important role in anti-cancer therapies." (PMID 29088787, 2017). "Mechanistic studies demonstrate that the rs7911488 C allele leads to low-expression of miR-1307-3p, high-expression of TYMS, and consequently insensitivity of cancer cells to capecitabine-based treatment." (PMID 29088787, 2017). "In the C-allelic patients, miR-1307-3p is down-regulated and TYMS, a direct target of miR-1307-3p, is over-expressed, which leads to insensitivity of cancer cells to capecitabine chemotherapy." (PMID 29088787, 2017). "It is thus of note that TYMS overexpression remains a strong prognostic feature, even if the analysis was limited to cancers harboring one or more of these deletions." (PMID 25762627, 2015).
cancer (continued). "Although other studies have suggested that TYMS expression holds potential as a predictor of responsiveness to pemetrexed treatment in advanced cancer patients, prospective studies are necessary to confirm these findings in NSCLC patients." (PMID 26502926, 2015). "In the present study, we investigated the effects of TYMS gene overexpression on the sensitivity of advanced cancer cells to pemetrexed." (PMID 26502926, 2015). "Among cancers with one, two, or all three of these deletions, there was a continuous increase of TYMS expression with the number of deletions (p < 0.0001)." (PMID 25762627, 2015). "The rapidly increasing evidence for a relevant role of TYMS in cancer is also of potential therapeutic interest since some of the widely used cytotoxic drugs including 5-fluorouracil (5-FU) and capecitabine exert their anticancer effects by inhibiting TYMS." (PMID 25762627, 2015). "TYMS expression was higher in neoplastic than in normal prostate epithelium and was detectable in 72.9% of 10,223 interpretable cancers." (PMID 25762627, 2015). "Of note, TYMS is a target of 5-fluorouracil, a chemotherapeutic drug used to treat a large variety of cancers." (PMID 25669981, 2015). "5-FU sensitivity and patients’ survival have been inversely related to the level of TYMS protein and enzymatic activity in cancer cells, and 5-FU-resistant tumors commonly express high levels of TYMS protein." (PMID 26416450, 2015). "Accordingly, TYMS expression is a rate-limiting feature for cell proliferation and also for cancer growth." (PMID 25762627, 2015). "This latter scenario is to some extent supported by the tendency towards an even higher TYMS expression in cancers with co-deletion of 3p, 5q or 6q." (PMID 25762627, 2015). "Cancer subtypes were characterized by (a) differential expression of treatment target genes as TYMS, HER2, and HER3 and (b) overrepresentation of treatment-related pathways like cell cycle, DNA repair, and ERBB pathways." (PMID 25325012, 2014). "For example, the aberrant regulation of ERCC1, TYMS, TUBB3, RRM1 and TOP2A is associated with the abnormal proliferation of cancer cells, according to the hallmarks of cancer that were proposed previously." (PMID 24926347, 2014). "Due to this critical function, TYMS has been a major target of anti-cancer drugs for the past 50 years." (PMID 23915286, 2013). "The immortalized normal foetal astrocyte SVGp12, which only expressed TYMS at low levels, was 4- to 20-fold less sensitive to raltitrexed than any of the cancer cell lines." (PMID 21365010, 2011). "The immunhistochemical staining of the corresponding protein in HPA demonstrated that TYMS is differentially expressed between normal and cancer samples, and indeed follows a characteristic outlier profile as predicted by the GTI." (PMID 21365010, 2011). "Immortalized normal foetal astrocytes (SVGp12) were 4- to 2-fold less sensitive to raltitrexed than the four cancer cell lines tested, which all expressed similarly high levels of TYMS." (PMID 21365010, 2011). "Evidently, TYMS inhibitor Pemetrexed should not be used in any future EXO1 therapeutic combinations in FA-deficient cancers." (PMID 41006228, 2025). "Of these, key cancer-associated genes shown to be upregulated by the SySa fusion were downregulated by TAK-981 treatment, including CDX2, HOXA10, SUZ12, TYMS, AURKB, and HOXC10 and SMC2." (PMID 40804185, 2025). "For tumors that have completed EMT, one study observed that TYMS knockdown could potentially increase metastasis, as cancer cells in a partial EMT state are known to exhibit a higher metastatic potential." (PMID 40075750, 2025). "TYMS positivity was related to PD‐L1 expression across most cancer types." (PMID 38279895, 2024). "Overall, these data suggest that loss of Ink4a/Arf gene function may cooperate with ectopic aberrant TYMS levels to accelerate genomic instability that would promote cancer development and metastases." (PMID 37106126, 2023).
cancer (continued). "In addition, an association between cancer stemness, poor prognosis of HCC and up-regulation of key enzymes of pyrimidine biosynthesis, such as deoxythymidylate kinase (DTYMK), thymidylate synthase (TYMS) and thymidine kinase 1 (TK1), has been described." (PMID 37108625, 2023). "Previously, it was reported that TYMS mRNA includes several miRNAs, including miR-433 and miR-203 that negatively regulate TYMS expression; this in turn, promotes 5-FU chemosensitivity of cancer cells." (PMID 36759799, 2023). "This time point could be defined as the responsive phase to 5-FU-based therapy before experiencing the acute induction of TYMS as we showed before, and also suggest for the dominant tumor suppressor nature of miRNAs in cancer." (PMID 37648713, 2023). "TYMS is often overexpressed in highly proliferative cells, especially in cancer cells." (PMID 37949226, 2023). "TYMS is a widely used cancer therapy target and thus its inhibition could contribute to the therapeutic effects of azacitidine and decitabine." (PMID 36380143, 2023). "Furthermore, other rate-limiting enzymes, such as thymidylate synthase (TYMS), thymidine kinase 1 (TK1), and deoxythymidylate kinase (DTYMK), are upregulated in HCC and are associated with poor prognosis and cancer stemness." (PMID 36835122, 2023). "GNB3, TRH, and TYMS also play important roles in human cancers." (PMID 35494074, 2022). "Accordingly, it can be expected that at least a few different miRNAs regulate the levels of the proteins encoded by TYMS and DPYD, and that altering the levels of these miRNAs may also contribute to reducing the sensitivity of cancer cells to 5FU." (PMID 35922756, 2022). "Some studies have connected TYMS expression to cancer development." (PMID 35740289, 2022). "In addition, it has been recently proposed that TYMS is directly involved in the epithelial-to-mesenchymal transition (EMT) of cancer cells." (PMID 35740289, 2022). "Moreover, this high expression level of TYMS has been found to be correlated with the development of poor 5-FU sensitivity in cancer cells." (PMID 34947902, 2021). "Thymidylate synthase (TYMS) is a critical target for cancer chemotherapy." (PMID 34970479, 2021). "However, some signaling proteins were found to be common regulatory molecules among the three cancers whereas terminal enzymes, such as EZH2, ENO2, RRM2, and TYMS, were found to be commonly regulated in all the cancers by three different regulatory mechanisms." (PMID 34790674, 2021). "Increasing evidence has suggested that TYMS continues as a critical therapeutic target for several cancer drugs, in addition to the discoveries that prove the participation of TYMS in different cancers, including LUAD." (PMID 34818974, 2021). "To confirm the PARIS predictions and test the sensitivity of cancer cells to TYMS inhibition, we treated a panel of cell lines with different CDKN2A genetic backgrounds with increasing doses of PMX (ranging from 10 nM to 15 μM) and measured cell viability as a readout for synthetic lethality." (PMID 34454516, 2021). "Increasing bench and clinical data has suggested that TYMS expression level might be an important determinant of cancer response to 5-FU-included chemotherapy." (PMID 34947902, 2021). "Indeed, using cancer cell lines to confirm the TYMS dependency predicted by PARIS, we discovered that the most robust effects can be observed in those lines where TYMP is expressed at high levels and CDKN2A is mutated or deleted." (PMID 34454516, 2021). "Finally, the HpTYMS-G4-T PPRH targeting the complementary strand of the G4FS decreased both TYMS mRNA and protein levels in cancer cells, leading to cell death and showing a synergic effect in combination with 5-FU." (PMID 32708710, 2020). "Thymidylate synthase (TYMS) enzyme is an anti-cancer target given its role in DNA biosynthesis." (PMID 32708710, 2020).